TOMT (transmembrane O-methyltransferase)
Description:
Catalyzes the O-methylation, and thereby the inactivation, of catecholamine neurotransmitters and catechol hormones (By similarity). Required for auditory function. Component of the cochlear hair cell's mechanotransduction (MET) machinery. Involved in the assembly of the asymmetric tip-link MET complex. Required for transportation of TMC1 and TMC2 proteins into the mechanically sensitive stereocilia of the hair cells. The function in MET is independent of the enzymatic activity (By similarity).
Synonyms: COMT2
Gene: Protein-coding gene on chromosome 11 (72,103,506 to 72,110,781, forward strand). Ensembl gene ENSG00000284844.
Subcellular location: Membrane (Isoform 1); Cytoplasm (Isoform 2); Endoplasmic reticulum
Genetic constraint (gnomAD): Loss-of-function variants: 23 observed, 21.01 expected, observed/expected ratio (o/e) 1.09, 90% interval 0.79 to 1.55. The upper end of that interval is the gene's LOEUF score, 1.55, which puts it in group 6 of 6, group 1 being the genes least tolerant of losing a copy. Missense variants: 331 observed, 335.84 expected, observed/expected ratio (o/e) 0.99, 90% interval 0.9 to 1.08. Synonymous variants: 132 observed, 143.49 expected, observed/expected ratio (o/e) 0.92, 90% interval 0.8 to 1.06.
Homologues: Orthologues: chimpanzee LRTOMT (99% identical), macaque LRTOMT (98% identical), rabbit TOMT (95% identical), pig TOMT (94% identical), dog TOMT (94% identical), guinea pig TOMT (94% identical), mouse Tomt (93% identical), rat Lrtomt (92% identical), zebrafish tomt (58% identical), Caenorhabditis elegans comt-3 (15% identical), Caenorhabditis elegans comt-2 (14% identical), Caenorhabditis elegans comt-4 (13% identical), and 1 more. Paralogues in human: COMT (35% identical), COMTD1 (19% identical).
Diseases named in the same sentence as TOMT in open-access papers:
TOMT is named in the same sentence as 3 diseases in open-access papers, as found by Europe PMC text mining. Sharing a sentence is not in itself a finding about the gene and the disease. The quoted sentences say what the papers report.
deafness (2 papers, 2017). An inherited or acquired condition characterized by the complete loss of the ability to hear from one or both ears. "Based on these data, it was speculated that TOMT acts as a catechol O-methyltransferase in vivo, and that the deafness phenotype of the mouse mutant was caused by hair-cell degeneration resulting from a failure to properly metabolize catecholamines." (PMID 28534737, 2017).
non-syndromic deafness (1 paper, 2017). "Transmembrane O-methyltransferase (TOMT/LRTOMT) is responsible for non-syndromic deafness DFNB63." (PMID 28534737, 2017).
TOMT also shares sentences with these, for which no sentence is quoted: hearing loss (1 paper).